CALR (calreticulin)
Description:
Calcium-binding chaperone that promotes folding, oligomeric assembly and quality control in the endoplasmic reticulum (ER) via the calreticulin/calnexin cycle. This lectin interacts transiently with almost all of the monoglucosylated glycoproteins that are synthesized in the ER. Interacts with the DNA-binding domain of NR3C1 and mediates its nuclear export. Involved in maternal gene expression regulation. May participate in oocyte maturation via the regulation of calcium homeostasis (By similarity). Present in the cortical granules of non-activated oocytes, is exocytosed during the cortical reaction in response to oocyte activation and might participate in the block to polyspermy (By similarity).
Synonyms: RO; SSA; cC1qR; CRT; FLJ26680; CALR1; HEL-S-99n
Tractability: Small molecule: a structure with a bound ligand is known. Antibody: UniProt places it where antibodies can reach, with high confidence; its Gene Ontology location is reachable by antibodies, with high confidence; UniProt predicts a signal peptide or a membrane-spanning region. PROTAC: ubiquitination databases record sites on it; its protein half-life has been measured.
Gene: Protein-coding gene on chromosome 19 (12,938,578 to 12,944,490, forward strand). Ensembl gene ENSG00000179218.
Subcellular location: Endoplasmic reticulum lumen; Cytoplasm, cytosol; Secreted, extracellular space, extracellular matrix; Cell surface; Sarcoplasmic reticulum lumen; Cytoplasmic vesicle, secretory vesicle, Cortical granule; Cytolytic granule
Subcellular location (Human Protein Atlas): Endoplasmic reticulum
Pathways (Reactome):
Disease: Assembly of Viral Components at the Budding Site; Maturation of DENV proteins
Immune System: Antigen Presentation: Folding, assembly and peptide loading of class I MHC; ER-Phagosome pathway
Vesicle-mediated transport: Scavenging by Class A Receptors; Scavenging by Class F Receptors
Cellular responses to stimuli: ATF6 (ATF6-alpha) activates chaperone genes
Metabolism of proteins: Calnexin/calreticulin cycle
Gene Ontology:
Molecular function: calcium ion binding; complement component C1q complex binding; integrin binding; mRNA binding; nuclear androgen receptor binding; nuclear export signal receptor activity; protein binding; protein folding chaperone; protein-macromolecule adaptor activity; RNA binding; ubiquitin protein ligase binding; carbohydrate binding; DNA binding; zinc ion binding; hormone binding; iron ion binding; peptide binding
Biological process: cellular senescence; negative regulation of DNA-templated transcription; negative regulation of intracellular steroid hormone receptor signaling pathway; negative regulation of neuron differentiation; negative regulation of retinoic acid receptor signaling pathway; negative regulation of transcription by RNA polymerase II; negative regulation of translation; negative regulation of trophoblast cell migration; peptide antigen assembly with MHC class I protein complex; positive regulation of cell cycle; positive regulation of cell population proliferation; positive regulation of dendritic cell chemotaxis; positive regulation of endothelial cell migration; positive regulation of substrate adhesion-dependent cell spreading; protein export from nucleus; protein folding; protein localization to nucleus; protein maturation; protein stabilization; ERAD pathway; intracellular calcium ion homeostasis; nuclear receptor-mediated glucocorticoid signaling pathway; positive regulation of phagocytosis; protein folding in endoplasmic reticulum; regulation of apoptotic process; and 13 more
Cellular component: cell surface; cytolytic granule; cytoplasm; cytosol; endoplasmic reticulum; endoplasmic reticulum lumen; extracellular exosome; extracellular region; focal adhesion; membrane; MHC class I peptide loading complex; nuclear envelope; nucleus; perinuclear region of cytoplasm; ribosome; cortical granule; endocytic vesicle lumen; endoplasmic reticulum-Golgi intermediate compartment membrane; lumenal side of endoplasmic reticulum membrane; phagocytic vesicle membrane; sarcoplasmic reticulum lumen; acrosomal vesicle; endomembrane system; endoplasmic reticulum quality control compartment; external side of plasma membrane; and 7 more
Genetic constraint (gnomAD): Loss-of-function variants: 14 observed, 51.75 expected, observed/expected ratio (o/e) 0.27, 90% interval 0.18 to 0.42. The upper end of that interval is the gene's LOEUF score, 0.42, which puts it in group 1 of 6, group 1 being the genes least tolerant of losing a copy. Missense variants: 475 observed, 549.16 expected, observed/expected ratio (o/e) 0.86, 90% interval 0.8 to 0.93. Synonymous variants: 239 observed, 217.96 expected, observed/expected ratio (o/e) 1.1, 90% interval 0.99 to 1.22.
Cancer hallmarks: invasion and metastasis (promotes); angiogenesis (promotes); proliferative signalling (promotes); escaping programmed cell death (promotes)
Homologues: Orthologues: macaque CALR (99% identical), chimpanzee CALR (99% identical), dog CALR (95% identical), mouse Calr (94% identical), guinea pig CALR (94% identical), pig CALR (94% identical), rat Calr (94% identical), zebrafish calr (73% identical), Caenorhabditis elegans crt-1 (60% identical). Paralogues in human: CALR3 (45% identical), CANX (42% identical), CLGN (40% identical).
Diseases named in the same sentence as CALR in open-access papers:
CALR is named in the same sentence as 291 diseases in open-access papers, as found by Europe PMC text mining. Sharing a sentence is not in itself a finding about the gene and the disease. The quoted sentences say what the papers report.
myeloproliferative neoplasm (182 papers, 2014 to 2026). A clonal hematopoietic stem cell disorder, characterized by proliferation in the bone marrow of one or more of the myeloid (i.e., granulocytic, erythroid, megakaryocytic, and mast cell) lineages. "This approach increased statistical power and allowed for more interpretable results while still capturing the common role of CALR mutations in the pathogenesis of myeloproliferative neoplasms." (PMID 39960584, 2026). "Calreticulin (CALR) mutations in myeloproliferative neoplasms (MPNs) create unique opportunities for targeted therapy." (PMID 41228192, 2025). "While somatic mutations in CALR are most famously established as key drivers in certain myeloproliferative neoplasms (MPNs), its role in solid tumors like bladder cancer is less direct and still under investigation." (PMID 41427025, 2025). "Here, we investigated EPO and thrombopoietin (TPO) induced SOCE and PLCγ1 activation in hematopoietic cells exhibiting activating mutations in JAK2 and CALR which are disease-initiating events in myeloproliferative neoplasms (MPNs)." (PMID 38509561, 2024). "During her admission, a bone marrow biopsy was performed to evaluate for myeloproliferative neoplasm given her history of positive CALR mutation." (PMID 39759619, 2024). "Taken together, this study contributes to a deeper understanding of the specific molecular mechanisms underlying CALR-mutated myeloproliferative neoplasms." (PMID 39337361, 2024). "We also wanted to establish the association between the studied polymorphisms of the XPC, XPD, XPF, and XPG genes and the JAK2, CALR driver mutations and to identify possible predictors in the appearance of myeloproliferative neoplasms." (PMID 38541232, 2024). "Third, CALR-mutated myeloproliferative neoplasms (MPNs) have been shown to induce a favorable T-cell response to possible ICI therapy." (PMID 38200372, 2024). "CALR encodes mainly involved in protein folding and quality control and it is closely related to myeloproliferative neoplasms." (PMID 39590360, 2024). "Numerous pathogenic CALR exon 9 mutations have been identified in myeloproliferative neoplasms (MPN), with type 1 (52bp deletion; CALRDEL) and type 2 (5bp insertion; CALRINS) being the most prevalent." (PMID 37240094, 2023). "Overview of pathogenic mechanisms of mutant calreticulin (CALR) in myeloproliferative neoplasms (MPN) and potential ways to target the mutant calreticulin neoantigen by therapeutic monoclonal antibodies (mAb)." (PMID 37551061, 2023). "While further studies are needed to investigate MYO6 regulation of lymphoma cell dynamics and to design novel therapeutic approaches, a monoclonal antibody targeting the neoepitope generated by mutated CALR in myeloproliferative disorders has been generated." (PMID 38035116, 2023). "Till date there are limited studies on the use of Calreticulin immunohistochemistry as a diagnostic tool for myeloproliferative neoplasms." (PMID 34514582, 2022). "In myeloproliferative neoplasms, CALR gene mutations are recurrent events, and it is well-known that stress-induced CALR exposure on the cell surface is considered a prophagocytic signal mediating immunogenic cell death." (PMID 35892824, 2022). "We evaluated the effects of the CALR mutant type and burden on the phenotype of CALR-mutated myeloproliferative neoplasms (MPN)." (PMID 36359414, 2022). "We describe a remarkable case of monozygotic twins presenting with CALR mutation-positive myeloproliferative neoplasms (MPNs) (aged 37 and 38 years), with a clinical phenotype of primary myelofibrosis." (PMID 35637336, 2022). "The patient suffered from hemolytic PNH associated with CALR+ myeloproliferative neoplasm and was heavily transfusion dependent despite eculizumab therapy." (PMID 36532073, 2022).
myeloproliferative neoplasm (continued). "One example of this is mutations in the calreticulin (CALR) gene in patients with myeloproliferative neoplasms, with mutant-CALR eliciting antigen-specific responses from both CD4 + and CD8 + T cells, suggesting potential as a shared neoantigen." (PMID 35672823, 2022). "To identify potential targeted therapies for CALR mutated myeloproliferative neoplasms, we searched for small molecules that selectively inhibit the growth of CALR mutated cells using high-throughput drug screening." (PMID 34333533, 2021). "Diagnostic and treatment response criteria for the JAK2/CALR/MPL mutation-related myeloproliferative neoplasms (MPNs) are largely based on bone marrow (BM) biopsy results." (PMID 33879266, 2021). "Calreticulin del52 and ins5 mutations induce two phenotypically distinct myeloproliferative neoplasms in patients." (PMID 32985500, 2020). "Somatic mutations of calreticulin have recently been reported in a subset of myeloproliferative neoplasms (MPNs)." (PMID 33014341, 2020). "Mutation of CALR (Exon9) L367fs*46 was found positive in the detection for myeloproliferative neoplasm associated genes." (PMID 32374950, 2020). "In this study, we demonstrated a rapid, low cost and sensitive detection of Calreticulin mutations by a PCR based amplicon length differentiation assay for diagnosis of myeloproliferative neoplasms." (PMID 31248375, 2019). "In 2013, two groups reported the discovery of mutations in the CALR gene in Myeloproliferative Neoplasms (MPNs), particularly in 60–80% of JAK2 and MPL unmutated Essential Thrombocythemia (ET) and Primary Myelofibrosis (PMF) patients." (PMID 31332222, 2019). "In this light, we performed OXR1 silencing in CD34+ cells, which are the target cells of CALR mutation and from whom the myeloproliferative disease originates." (PMID 31332222, 2019). "Disease-initiating mutations in calreticulin (CALR), an endoplasmic reticulum (ER) chaperone protein, are present in approximately 40% of myeloproliferative neoplasms (MPN)." (PMID 30400835, 2018). "Effects of the CALR mutations identified so far in patients with myeloproliferative neoplasm on the intrinsic disorder-based interactivity of the protein." (PMID 29218307, 2017). "In general, the biological consequences of somatic CALR SNPs associated with cancer are far less characterized than those of the mutant proteins found in myeloproliferative neoplasms." (PMID 29218307, 2017). "Surprisingly, the phenotype of myeloproliferative disorders associated with CALR mutations includes growth factor independent activation of JAK2, and these patients respond to treatment with JAK inhibitors, such as Ruxolitinib." (PMID 29218307, 2017). "Recent advances in the diagnostic of myeloproliferative neoplasms (MPNs) discovered CALRETICULIN (CALR) mutations as a major driver in these disorders." (PMID 26202929, 2016). "Recently, frameshift extension mutations in CALR (encoding calreticulin) were identified in myeloproliferative neoplasms and WT1 extension mutants have been described in Wilms kidney tumours." (PMID 27588951, 2016). "CALR mutations are identified in about 30% of JAK2/MPL-unmutated myeloproliferative neoplasms (MPNs) including essential thrombocythemia (ET) and primary myelofibrosis." (PMID 27716741, 2016). "A relationship between lupus autoimmunity, myeloproliferative disorders and calreticulin mutations is reminiscent of the incidence of scleroderma in cancer patients with RNA polymerase IIIA mutations." (PMID 27483354, 2016). "Somatic mutations in the CALR gene have been recently identified as acquired alterations in myeloproliferative neoplasms (MPNs)." (PMID 26375990, 2015). "For instance, mutations in CALR drive about one-fifth of myeloproliferative neoplasms (MPNs)." (PMID 39997326, 2025).
myeloproliferative neoplasm (continued). "Genetic testing in this patient was essential to exclude mutations associated with hematologic malignancies, such as JAK2 or CALR mutations, which could explain myeloproliferative neoplasms or other findings." (PMID 40969728, 2025). "In this way, the introduction of mutations similar to those causing myeloproliferative neoplasms in humans could allow the identification of the JAK2/STAT-independent effects of mutant calreticulin." (PMID 39519157, 2024). "It has been demonstrated previously that human leukocyte antigen class I (HLA-I) and class II (HLA-II) alleles may modulate JAK2 V617F and CALR mutation (CALRmut)-associated oncogenesis in myeloproliferative neoplasms (MPNs)." (PMID 39351227, 2024). "Intriguingly, CALR is frequently mutated in various human cancers such as myeloproliferative neoplasms (MPNs), and a recent study shows that COVID-19 patients with MPNs are significantly at higher risk of arterial thrombosis and death compared to non-MPN patients." (PMID 38067122, 2023). "CALR mutations had an important role in myeloproliferative neoplasms." (PMID 38049825, 2023). "CALR mutations are known drivers of myeloproliferative neoplasms and may therefore contribute to a clonal advantage and expansion even after the BCR::ABL1 clone has been eradicated." (PMID 35902731, 2022). "CALR is found in myeloproliferative neoplasms (MPN) and represents an MPN-driver mutation." (PMID 34025649, 2021). "Antiplatelet therapies discussed earlier therefore pose a risk in myeloproliferative neoplasms, as patients with specific subgroup mutations, including CALR-positive-ET patients and patients with extremely high platelet counts, are at higher risk of bleeding when receiving low-dose aspirin." (PMID 34831257, 2021). "Calreticulin is a chaperone protein, which is associated with myeloproliferative diseases." (PMID 34449535, 2021). "Mutation of CALR, a typical gene mutation in myeloproliferative disorders, was also detected." (PMID 32374950, 2020). "The driver mutations JAK2V617F, MPLW515L/K and CALR influence disease phenotype of myeloproliferative neoplasms (MPNs) and might sustain a condition of chronic inflammation." (PMID 28228104, 2017). "Conversely, the putative JAK2-dependent phosphorylation sites present in wild-type CALR suggest that in myeloproliferative disorders JAK2 mutations may affect the function of this protein." (PMID 29218307, 2017). "Whether CALR mutations in myeloproliferative neoplasms predispose to the acquisition of additional malignancies, particularly lymphoproliferative disorders, is not yet known." (PMID 26904322, 2016). "CALR trails JAK2 as the second most mutated gene in myeloproliferative neoplasms (MPNs)." (PMID 26377485, 2016). "Very recently, mutations in calreticulin gene were detected in myeloproliferative neoplasms (MPN)." (PMID 25918716, 2015). "Calreticulin (CALR) mutations are prevalent in 20%-30% of patients with BCR::ABL1-negative myeloproliferative neoplasms (MPN)." (PMID 41532194, 2026). "More recently, a pair of MZ twins were diagnosed with primary myelofibrosis, a type of myeloproliferative neoplasm (MPN), at the ages of 37 and 38 years and were found to share the same somatic mutation in the CALR gene." (PMID 38275407, 2024). "Calreticulin (CALR) frameshift mutations represent the second cause of myeloproliferative neoplasms (MPN)." (PMID 37019903, 2023). "Mutations in calreticulin are one of the key disease‐initiating mutations in myeloproliferative neoplasms (MPN)." (PMID 37551061, 2023). "In addition, mutated CALR drives JAK/STAT signaling in myeloproliferative neoplasms." (PMID 34072546, 2021). "CALR mutations are a revolutionary discovery and represent an important hallmark of myeloproliferative neoplasms (MPN), especially essential thrombocythemia and primary myelofibrosis." (PMID 33806036, 2021).